RAB11A (RAB11A, member RAS oncogene family)
Diseases named in the same sentence as RAB11A in open-access papers (continued):
Sharing a sentence is not in itself a finding about the gene and the disease.
Atrophy (1 paper, 2014). Any weakening or degeneration, especially through lack of use. "Conversely, the localisation of Rab11a is altered in the intestinal epithelial cells of Rab8a knockout mice and in a microvillus atrophy patient, which has a mutation in the myosin Vb gene." (PMID 25527643, 2014). "Conversely, Rab11a is mislocalised in Rab8a knockout mice and in a microvillus atrophy patient, which has a mutation in the myosin Vb gene." (PMID 25527643, 2014). "We also observed that the localisation of Rab11a in the small intestinal tissue from a microvillus atrophy patient was different from that in a healthy intestinal tissue." (PMID 25527643, 2014). "However, in the small intestine of the microvillus atrophy patient, Rab11a localised closer to the nucleus." (PMID 25527643, 2014).
Chlamydia infections (1 paper, 2009). "Taken together, our data show Rab6A and Rab11A are essential for Chlamydia-induced Golgi fragmentation and further strengthens the hypothesis that Golgi fragmentation can influence the outcome of Chlamydia infections." (PMID 19816566, 2009).
coinfection (1 paper, 2021). The simultaneous infection of a host by multiple pathogen species. "In the context of mixed infections, we furthermore find that TNT/Rab11a-mediated transfer readily leads to cellular coinfection and reassortment." (PMID 34473799, 2021). "For subsequent analysis of co-infection via TNT/Rab11a mediated genome transfer, these experiments were set up using two IAV strains, NL09 ΔHAVenus WT and NL09 ΔHAScarlet VAR viruses." (PMID 34473799, 2021). "Since we observed that infectious progeny could be generated via Rab11a-mediated genome transfer through TNTs, we hypothesized that this process could also mediate co-infection and therefore reassortment." (PMID 34473799, 2021).
colitis (1 paper, 2021). Inflammation of the colon. "By comparison, because of an enhanced YAP nuclear localization and failed junctional delivery of YAP upon tissue damage, DSS-treated Rab11a-deficient mice had decreased epithelial differentiation and impaired epithelial restoration, leading to exacerbated colitis." (PMID 34058200, 2021).
dementia (1 paper, 2015). Loss of intellectual abilities interfering with an individual's social and occupational functions. "aSyn associates with Rab3a, Rab5 and Rab8 in dementia with LB patients and mouse models, and an interaction between endocytosed aSyn and Rab11a has been observed in mammalian cells." (PMID 25305083, 2015).
developmental delay (1 paper, 2025). "In summary, we present a case of a RAB11A-related NDD patient, predominantly characterized by global developmental delay, motor disorder and brain anomalies." (PMID 40959816, 2025).
endotoxemia (1 paper, 2023). "Thus, Rab11a in macrophages has a fundamental check-point role in TWIK2 plasmalemmal translocation and regulating NLRP3 inflammasome activation and endotoxemia-induced inflammatory lung injury." (PMID 37158595, 2023).
inflammatory bowel disease (1 paper, 2025). A spectrum of small and large bowel inflammatory diseases of unknown etiology. "The RAB11A gene is associated with many diseases, such as NDDs, neurodegenerative diseases, tumors, and inflammatory bowel disease." (PMID 40959816, 2025).
malabsorption syndrome (1 paper, 2023). A syndrome resulting from the inadequate absorption of nutrients in the small intestine. "In aprevious paper, we described that ChREBP, Rab11a, and GLUT5 deletions cause intestinal FMin mice, which in turn leads to malabsorption syndrome manifestations, and we willnot repeat them here." (PMID 37674366, 2023). "However, in mice with targeted deletion of Rab11a in smallintestinal epithelial cells, fructose feeding failed to induce GLUT5 expression in the smallintestine, and the mice exhibited malabsorption syndrome, suggesting that Rab11a is one ofthe factors regulating GLUT5 expression." (PMID 37674366, 2023).
parasite (1 paper, 2021). "The changes in Golgi morphology and subcellular location induced by the loss of GTPase activity (Arf1, Rab1a or Rab11a) and by the parasite infection were visualized by staining against the GM130." (PMID 34013963, 2021).
respiratory infections (1 paper, 2025). "Our findings suggest that YT-DRI inhibits viral replication by disrupting RAB11A-dependent trafficking, offering a promising strategy for developing broad-spectrum antivirals against respiratory infections." (PMID 40259361, 2025).
synucleinopathy (1 paper, 2015). A neurodegenerative disease that is characterized by the abnormal accumulation of aggregates of alpha-synuclein protein in neurons, nerve fibers or glial cells. "This process appears to be Rab11a-dependent, which likely explains Rab11a's involvement in synucleinopathy." (PMID 26617485, 2015).
thyroid autoimmune disease (1 paper, 2021). "Also, we separated non-thyroid autoimmune disease (bvFTD-nonthyroid, N=8) from the bvFTD-autoimmune group and compared them to bvFTD-nonautoimmune, and found that 3 proteins were significantly altered; increased – ATP5B, RAB11A; decreased – HRG." (PMID 34539672, 2021).
triple-negative breast carcinoma (1 paper, 2023). An invasive breast carcinoma which is negative for expression of estrogen receptor (ER), progesterone receptor (PR), and human epidermal growth factor receptor 2 (HER2). "We next sought to confirm our findings using BT20 triple-negative breast cancer cells, which express Rab4a, Rab4b, Rab11a, Rab11b and Rab25." (PMID 37232246, 2023).
infection (68 papers, 2009 to 2026). The state of being infected such as from the introduction of a foreign agent such as serum, vaccine, antigenic substance or organism. "In three independent Rab11a KO clones, infection with an H5N1 strain (A/Vietnam/1203/04, low pathogenic; MOI = 0.001) showed ~1000-fold lower replication as compared to control cells." (PMID 33970958, 2021). "First, we assessed the susceptibility and permissiveness of Rab11a KO cells by single cycle infection experiments using different IAV expressing GFP or luciferase reporters." (PMID 33970958, 2021). "At later time points in infection, inclusions containing vRNPs and RAB11A can be observed throughout the cytoplasm." (PMID 40668844, 2025). "The large number of proteins with reduced or increased abundance demonstrate that the proximity interactome of RAB11A is strongly disrupted upon infection." (PMID 40668844, 2025). "Confocal microscopy revealed increased localization of TfR1 at the cell membrane following PRV-GFP infection, which was markedly reduced in Rab11a-knockdown cells." (PMID 40891826, 2025). "Consistently, in HT29 cells, protein expression of LC3B (specifically the LC3B-I form) and RAB11A also decreased significantly 24 h post-infection in miR-215 mimic-transfected cells." (PMID 39943201, 2025). "Similar results were obtained by knocking down the autophagic ATG16L1 protein, also found enriched in the vicinity of RAB11A upon infection in our proximity labeling experiments, and known to be involved in PI4P turnover." (PMID 40668844, 2025). "To correlate these location changes with HPIV3 infection, we conducted an infection assay in cells expressing RAB11A, RAB11ADN, or RAB11ACA." (PMID 40259361, 2025). "Compared to wild-type (WT) HeLa cells, RAB11A-KO cells displayed a significant reduction in infectious particle production at 24 h post-infection (hpi)." (PMID 40259361, 2025). "Downstream approaches including viral entry by-pass, intracellular viral genome quantification by qPCR, Western blot analyses, and Luciferase reporter assays allowed determine the stage of the infection cycle the top candidate, RAB11A was involved in." (PMID 38943128, 2024). "As infection progresses, vRNPs and Rab11a endosomes concentrate further at the ERES to form viral inclusions that share properties with bona fide liquid condensates." (PMID 37983294, 2023). "Rab11a was used as a proxy to track movement of viral inclusions (magenta), whereas Sir-Tubulin dye was added at the time of infection to visualize microtubules (green)." (PMID 37983294, 2023). "We observed that at late stages of infection, vRNPs were able to internally rearrange in normal conditions as well as when Rab11a was overexpressed." (PMID 37013374, 2023). "(C) Boxplot depicting the fold change in the ratio of cytoplasmic to nuclear vRNPs concentration at different times of infection, with endogenous or overexpressed Rab11a; p<0.001; Kruskal Wallis Bonferroni treatment." (PMID 37013374, 2023). "When overexpressing Rab11a (right side of each graph), cytosolic vRNPs also accumulated in viral inclusions that increased with infection (from 0.243±0.03 to 0.385±0.04 μm2), but were significantly bigger than viral inclusions in GFP expressing cells." (PMID 37013374, 2023). "The combined visual inspection of Rab11 distribution in mock and infected cells with transferrin (Tf) recycling assays allows determining the fate of Rab11a endosomes in infection." (PMID 37983294, 2023). "In conclusion, the infection of T. gondii resulted in up-regulation of host cell rab11a transcription, and the Rab11A abundance remains unchanged in wild-type HeLa cells while decreased in autophagy deficiency mutant." (PMID 36532461, 2022). "In this study we demonstrate that the host factor Rab11a mediates the transport of viral genomes in the cell-cell spread of infection." (PMID 34473799, 2021).
infection (continued). "The production of viral progeny observed in this system further indicates that this Rab11a from the originally uninfected cell can then transport vRNPs back through the TNTs, mediating infection." (PMID 34473799, 2021). "To allow comparison to this prior work, we performed high MOI infections in Rab11a KO cells and similarly observed a 10-fold decrease in viral titers for H1N1 and H5N1 viruses." (PMID 33970958, 2021). "Previous Rab11a siRNA knock down (KD) studies showed a 5-10-fold decrease in viral titers for high MOI infections." (PMID 33970958, 2021). "We decisively show that productive infection can be mediated through this direct cell-to-cell route and find evidence that Rab11a can move through TNTs in a bidirectional manner to mediate IAV genome transfer." (PMID 34473799, 2021). "At later times during infection, NP-Tc puncta increased in size and co-localized with the cellular factor Rab11a prior to organized trafficking on the microtubule network." (PMID 33970958, 2021). "Both H1N1-GFP and H5N1-GFP viruses showed similar levels of infection (% GFP cells) in Rab11a KO and control A549 cells." (PMID 33970958, 2021). "Taken together, we propose a model in which Rab11A transport is altered during infection due to a change in the ratio of motor proteins on Rab11A-RE." (PMID 31911620, 2020). "Unexpectedly, infection with respiratory syncytial virus alters Rab11A motion in a manner opposite to IAV, suggesting that Rab11A is a common host component that is differentially manipulated by respiratory RNA viruses." (PMID 31911620, 2020). "Since we observed that NP, L, and C proteins all colocalized with Rab11a during infection, we next sought to address which of these proteins is important for the interaction of vRNPs with recycling endosomes." (PMID 32843550, 2020). "Expression of Myo5b-tail inhibited the recruitment of Rab11a and Tfn to the infection sites (yellow arrows), suggesting that Myo5b is involved in the trafficking of basolaterally internalized TfnR to the apical recycling endosomes at the infection sites." (PMID 31242273, 2019). "Here we show that early upon EPEC microcolony attachment to non-polarized host cells, EspF and Map prompt the recruitment of transferrin receptors (TfnR) and Rab11a-positive recycling endosomes to peripheral infection sites." (PMID 31242273, 2019). "If Tfn was internalized into the cells prior to exposure to Dyngo along with EPEC-wt, both Tfn and Rab11a clustered efficiently at infection sites." (PMID 31242273, 2019). "Infection with these strains also prompted the recruitment of Rab11a and Myo5b at infection sites, where EspF and Map staining partially overlapped with Rab11a and Myo5b, suggesting that the effector proteins reside in close proximity to the host proteins." (PMID 31242273, 2019). "Together, these results suggest that upon translocation, EspF and Map promote the redistribution and clustering of Rab11a/Tfn positive endosomes at peripheral infection sites to increase the endocytic turnover at the infected plasma membrane." (PMID 31242273, 2019). "Previously, we found that phosphoactive EGFR is retained in Rab5- and Rab11a-positive endosomes in infection." (PMID 30042195, 2018). "Further investigation of the transport of Rab11A and vRNP in live cells during a productive infection is needed and will help provide further information on the dynamics of vRNA assembly and the presence of a possible Rab11A-independent transport mechanism." (PMID 28724771, 2017). "Next, we performed GST pull-down assays with lysates prepared from infected cells using GST-RBD at 8 h post infection (at which the virus genome is actively transported) and the co-purified Rab11a was analyzed by western blotting with anti-Rab11a antibody." (PMID 26575487, 2015). "The results showed a significant increase in Rab11a expression following infection." (PMID 40891826, 2025).
infection (continued). "Interestingly, recent research indicates FIP binding to Rab11a remains unaffected during infection, hinting at a regulated process involving dynein in viral inclusion formation." (PMID 37983294, 2023). "As a consequence, Rab11a-regulated recycling function is impaired in infection." (PMID 37983294, 2023). "The similarity in ER alterations indicates that it is infection, and not Rab11a overexpression that changes the ER morphology, which leads to conclude that our observations are not an artifact caused by Rab11a overexpression." (PMID 37983294, 2023). "Our studies in Rab11a KO A549 cells showed a similar 10-fold decrease in viral titers during high MOI infections at 24hpi (H5N1 MOI = 1; H3N2 MOI = 5), suggesting that IAV genome assembly and cytoplasmic trafficking can occur in the complete absence of Rab11a, albeit less efficiently." (PMID 33970958, 2021). "We observed that infectious progeny could be recovered from co-cultures of infected Rab11a KO A549 cells with MDCK WSN HA cells, which was incongruous with our previous observation that Rab11a KO abrogated the cell-cell transmission of infection." (PMID 34473799, 2021). "To assess the effect of the Rab family on RSV replication, we depleted Rab1a, Rab2a, Rab4a, Rab5a, Rab6a, Rab7a, Rab8a, Rab9a, and Rab11a by treating A549 cells with specific siRNAs (or control siRNA) for 24 h, followed by infection with purified RSV A2 and incubation for another 36 h." (PMID 33504607, 2021). "To examine whether alteration of Rab11A transport in A549 cells is unique to IAV, we investigated whether infection with RSV also altered Rab11A movement (for sample dataset)." (PMID 31911620, 2020). "Interestingly, while Tfn, Rab5a and EEA1 showed very low levels of clustering at infection sites, Rab11a displayed significantly higher clustering at these sites." (PMID 31242273, 2019). "Data clearly show T3SS-dependent recruitment of the photoconverted Rab11a at bacterial infection sites, suggesting that type III secreted components elicit the shuttling of Rab11a/Tfn-positive endosomes from perinuclear recycling endosomes to peripheral infection sites." (PMID 31242273, 2019). "We asked whether vectorial shuttling of Tfn/Rab11a-positive endosomes takes place from perinuclear to peripheral infection sites." (PMID 31242273, 2019). "To minimise this limitation, we combined overexpressing Rab11a with a range of low and high levels of vRNPs (analysing the entire time course of infection) to understand if a combination of high levels of vRNPs and of Rab11a could synergistically change the material properties of IAV inclusions." (PMID 37013374, 2023). "Therefore, isolating the effect of infection on Rab11A motion could be confounded by analysis of all of the GFP-Rab11A puncta within a cell due to this nonhomogeneous association with IAV vRNP." (PMID 31911620, 2020). "We also examined colocalization of Rab11a with other viral proteins, including C proteins and polymerase L proteins, using a previously characterized strain with the L protein C-terminally fused to enhanced green fluorescent protein (SeV LeGFP) to visualize L protein during infection." (PMID 32843550, 2020). "Additionally, our focus on respiratory RNA viruses may not fully encompass the broader implications of RAB11A-dependent cellular trafficking pathways, which are implicated in the infection cycles of various viruses." (PMID 40259361, 2025). "Further validating the importance of GTP-bound RAB11A in HPIV3 infection, RAB11A-KO HeLa cells transfected with plasmids expressing RAB11A and RAB11ADN exhibited restored infection solely with active RAB11A, consistent with the VLP assay results." (PMID 40259361, 2025). "Among the >1900 proteins whose abundance in RAB11A proximity interactome was decreased upon infection, we found the RAB11FIP-1, -2, -3, -4, and -5 proteins, i.e., RAB11A effector proteins essential to the endosomal recycling process." (PMID 40668844, 2025).